IL1B (interleukin 1 beta)
Diseases named in the same sentence as IL1B in open-access papers (continued):
Sharing a sentence is not in itself a finding about the gene and the disease.
Graves disease (5 papers, 2014 to 2025). Graves' disease is an autoimmune disorder that leads to overactivity of the thyroid gland (hyperthyroidism).It is caused by an abnormal immune system response that causes the thyroid gland to produce too much thyroid hormones. "Genotypic frequencies and association given by the odds ratio (OR) and 95% confidence intervals (95% CI) between genetic variants in IL1B, TNFA, IL6, and IFNGR1, and Graves' disease and Hashimoto's thyroiditis." (PMID 25127106, 2014). "Polymorphisms in the IL6-174 G/C (rs1800795), TNFA-308 G/A (rs1800629), IL1B-511 C/T (rs16944), and IFNGR1-56 T/C (rs2234711) genes were assessed in a case-control study comprising 420 Hashimoto's thyroiditis patients, 111 Graves' disease patients and 735 unrelated controls from Portugal." (PMID 25127106, 2014). "The ability of Graves' disease patients with the +32204 GG genotype to fully methylate their DNA may correlate with the methylation levels of interleukin-1beta (IL-1β) and transforming growth factor-beta (TGF-β) promoter regions, impacting IL-1β and TGF-β production." (PMID 40290121, 2025).
Hashimoto thyroiditis (5 papers, 2014 to 2025). An autoimmune disorder caused by the production of autoantibodies against thyroid tissue. "In the Hashimoto’s thyroiditis cell model treated with IL-1β and IFN-γ, the decreased expression of Cav-1 can inhibit the activity of autophagy and downregulate the expression of autophagy-related protein LC3B-II." (PMID 41030451, 2025). "We determined that patients with Hashimoto’s thyroiditis had substantial levels of IL-1B, IL-8, and IL-12 and TNF-α, but that the levels of IL-6 and IL-12 were non-significant compared to the healthy control group." (PMID 37241088, 2023). "have examined the thyroid tissue of patients with Hashimoto’s thyroiditis and have found that the expression of Th1 cytokines interleukin-1β (IL-1β) and interferon-γ (IFN-γ) is higher than that of healthy individuals, while the expression of Cav-1 is lower than that of healthy individuals." (PMID 41030451, 2025). "The proinflammatory cytokine concentrations of IL-8, IL-10, IL-1B, and TNF-α were found to be significantly increased in patients with Hashimoto’s disease, who have anti-thyroid peroxidase antibodies and/or anti-thyroglobulin antibodies as compared to age- and sex-matched controls." (PMID 37241088, 2023). "In this study, IL-17, IL-1β and IL-6 levels were found to be markedly increased in the TG-immunized rats exposed to DBP, suggesting that Th17 and pro-inflammatory cytokines play an important role in DBP exacerbation of chronic lymphocytic thyroiditis." (PMID 29133889, 2017). "Chronic inflammation is also present in Hashimoto’s thyroiditis, an autoimmune thyroid disorder characterized by tissue damage, fibrosis, and the release of inflammatory cytokines including Interleukin 6 (IL-6), Tumor Necrosis Factor-alpha (TNF-α), and Interleukin 1 beta (IL-1β)." (PMID 40218202, 2025). "The concentrations of IL-8, 10, IL-1B, and TNF-α were significant higher in patients with Hashimoto’s disease (p < 0.05), whereas the concentrations of IL-6 and 12 were non-significant among patients with Hashimoto’s disease as compared to healthy controls (p > 0.05)." (PMID 37241088, 2023).
hemarthrosis (5 papers, 2020 to 2025). Bleeding into the joints. "During the acute phase (day 3), all M1 markers were elevated in response to hemarthrosis (Il6, Il1β, Nos2, Cxcl2 and Il1r1), whereby Il6 and Nos2 were suppressed to baseline levels by rhFVIII and mFcFVIII alike, without effects on Il1β, Cxcl2 and Il1r1." (PMID 40388523, 2025). "IL-1β, IL-6, and MCP1 are involved in inflammation and progression of hemarthrosis in HA mouse models, while in vitro studies utilizing human cartilage cultures have indicated that IL-1β blockade is more effective than TNFα blockade in reducing damage following exposure to blood." (PMID 32595650, 2020). "Indeed, when activated by erythrocyte phagocytosis, monocytes and macrophages were reported to produce IL‐1β and TNF‐α in the joint after hemarthrosis, which could explain the control of FLS expression by a negative feedback pathway of IL‐1α but this hypothesis needs to be confirmed." (PMID 33159500, 2020).
hemorrhagic stroke (5 papers, 2021 to 2025). A stroke caused by a bleed on the brain. "We found NLRP3 inhibition prevented both the increased IL-1β expression and the microglia morphology shift typical of hemorrhagic stroke." (PMID 34284798, 2021). "Traditionally, pro-inflammatory cytokines, such as IL-6 and TNF-α as well as IL-1β and matrix metalloproteinases (MMPs), have been studied in a wide range of medical conditions including ischemic and hemorrhagic stroke as a surrogate for predicting poor outcomes." (PMID 35927663, 2022). "In the acute phase of hemorrhagic stroke, activated microglia contribute to the clearance of cellular debris and secrete pro‐inflammatory cytokines such as TNF‐α, IL‐1β, and IL‐6, which can exacerbate neuronal injury if persistently elevated." (PMID 41363028, 2025). "Initially, we analyzed the levels of COX-2, IL-1β, and the upstream mediator JNK in BV2 cells cultured alone (PBS group) and in the presence of platelets derived from either healthy donors or hemorrhagic stroke patients." (PMID 39256999, 2024).
hip fracture (5 papers, 2013 to 2026). Traumatic or pathological injury to the hip in which the continuity of either the femoral head, femoral neck, intertrochanteric or subtrochanteric regions is broken. "However, TNFα, and IL1β did not correlate with depressive symptoms in the present study, nor did the hip fracture patient groups differ on these cytokines, other than for TNFα." (PMID 23876747, 2013).
hyperandrogenism (5 papers, 2022 to 2026). Excessive secretion of androgens from the adrenal glands or gonads. "While IL-6 plays a dual role (both pro- and anti-inflammatory), IL-1β is strictly pro-inflammatory, leading to ovarian inflammation and androgen excess." (PMID 40385768, 2025). "Compared to IL-6 and TNF-α, IL-1β has a more localised impact on ovarian dysfunction and hyperandrogenism." (PMID 40385768, 2025). "In a prior study, elevated levels of IL-1β were observed in hyperandrogenism-induced PCOS-like mice." (PMID 40830889, 2025). "Therefore, this axis connects hyperandrogenism, inflammation via IL-1β, and cell death, contributing to PCOS pathology." (PMID 40830889, 2025). "PCOS is considered to be a chronic inflammatory disease, and multiple inflammation-related genes (such as interleukin-1 beta (IL1B), prostaglandin-endoperoxide synthase 2 (PTGS2)), as well as granule cells(GCs) in the inflammatory environment of PCOS patients, have been linked to hyperandrogenism." (PMID 35787810, 2022). "Hormonally, LP suppressed hyperandrogenism, as evidenced by decreased testosterone, while rebalancing inflammatory mediators through IL-10 upregulation and concomitant reduction of TNF-α, IL-6, IL-1β, and MCP-1." (PMID 41624200, 2026). "The most pertinent finding was that the rats with hyperandrogenism had significantly higher levels of TNF-ɑ and IL-1β compared to the control rats; additionally, the ovaries in the rats receiving excess androgen were smaller and had numerous cysts that resemble PCOS in women." (PMID 37062827, 2023).
hyperphosphatemia (5 papers, 2021 to 2026). Abnormally high level of phosphate in the blood. "Other CKD-related factors, such as vitamin D3 deficiency and hyperphosphatemia, may also disturb the functions of the inflammasome, as vitamin D3 is crucial for NLRP3-dependent IL-1β secretion and hyperphosphatemia polarizes macrophages into the M2-like phenotype." (PMID 33430226, 2021).
hypersomnia (5 papers, 2015 to 2025). A sleep disorder characterized by excessive sleepiness. "In summary, there was a significant correlation between change in IL-1β and change in hypersomnia (ρ=−0.37, P=0.003) and between change in BDNF and change in hypersomnia (ρ=0.26, P=0.029)." (PMID 26241349, 2015). "The relationship of reduced IL-1β with reduced hypersomnia fits with previous research." (PMID 26241349, 2015). "Specifically, reductions in BDNF and IL-1β are related to reductions in hypersomnia." (PMID 26241349, 2015). "The fact that changes in IL-1β and BDNF were only related to changes in hypersomnia further support the need to identify biological markers that differentiate across different symptom profiles." (PMID 26241349, 2015). "Reduction in hypersomnia was correlated with reductions in BDNF (ρ=0.26, P=0.029) and IL-1β (ρ=0.37, P=0.002)." (PMID 26241349, 2015).
hypogonadism (5 papers, 2018 to 2025). A disorder characterized by decreased function of the gonads. "In brief, in an animal model of hypogonadism, reduced testosterone levels were associated to elevated inflammatory cytokines such as IL-6, IL-1β, and TNF-α." (PMID 37298172, 2023). "One common observation in these studies is that higher levels of IL-6, IL-1β, TNF-α, and CRP were noted in men with testosterone deficiency (hypogonadism)." (PMID 30558178, 2018). "We found that male castration increased the recruitment of inflammatory cells and upregulated the expression of TNF-α and IL-6, similar to clinical reports that higher levels of IL-6, IL-1β, and TNF-α were noted in men with testosterone deficiency (hypogonadism)." (PMID 33475136, 2021). "Of note, animal and human studies have reported that hypogonadism is linked with pro-inflammatory cytokines which may adversely affect erectile function mainly in aging men because testosterone blocks a variety of cytokines, including TNF-α, IL-1β, and IL-649." (PMID 37045862, 2023).
interstitial cystitis (5 papers, 2021 to 2025). A rare chronic debilitating urogenital disease characterized by urinary frequency, urgency, and pelvic pain. "JNK also has been previously documented to have a role in the development of inflammation in interstitial cystitis, since its activation enhances the release of IL-1β and TNF-α." (PMID 40426893, 2025). "Interstitial Cystitis or Bladder Pain Syndrome (IC/BPS) is a heterogeneous condition characterized by elevated levels of inflammatory cytokines, IL-1β, IL-6, IL-8, IL-10, TNF-α, and is associated with debilitating symptoms of pelvic pain and frequent urination." (PMID 33923265, 2021).
interstitial lung disease (5 papers, 2010 to 2025). A diverse group of lung diseases that affect the lung parenchyma. "Next, we asked whether other cytokines and growth factors previously implicated in interstitial lung disease, such as TNF-α, IL1β and CTGF, alone or in combination with TGF-β1, would induce or alter the progression of EMT in HBECs." (PMID 20051102, 2010). "In addition, increased Eotaxin, IL10, IP10, and MCP1 are found in anti-MDA5 patients with interstitial lung disease; In patients with rapidly progressive interstitial lung disease (RP-ILD), IFNγ, IL1β and IL12 levels are considerably elevated." (PMID 35517781, 2022). "TNF-α also contributes to the pathophysiology of interstitial lung disease by inducing the apoptosis of epithelial cells and the sequential release of TGF-β, IL-1β, and IL-1 receptor antagonist (IL-1ra)." (PMID 20137099, 2010). "According to studies, HBP, IL-1β, and IL-8 were found to be useful markers for diagnosing pulmonary infection in lung-transplant patients and distinguishing from rejection, while high levels of HBP are also correlated to acute exacerbation of interstitial lung disease (AE-ILD)." (PMID 41007875, 2025).
intestinal tumors (5 papers, 2017 to 2024). "IL-1β appears to be dispensable for eradicating intestinal tumours because genetic ablation of type-I IL-1 receptor in hCEA-Tg/ApcMin/+ mice did not compromise the antitumour efficacy of PsV." (PMID 28397782, 2017). "The results found that PZH not only inhibited the increase in the number and volume of intestinal tumors in CAC mice but also suppressed the secretion of pro-inflammatory cytokines IL-6, TNF-α, and IL-1β in mouse serum." (PMID 39020410, 2024).
intracranial hemorrhage (5 papers, 2021 to 2023). Bleeding within the SKULL, including hemorrhages in the brain and the three membranes of MENINGES. "Within 4 hours after intracranial hemorrhage, neutrophil infiltration occurred around the hematoma, and the expression of IL-1β, TNF-α and pro-inflammatory protease increases significantly." (PMID 34511434, 2021). "Thus, we evaluated the effectiveness of siponimod in the expression of Th1-type inflammatory factors, including IFN-γ and IL-1β in the hemorrhagic brain." (PMID 37191423, 2023). "Another study also reported that UTI could attenuate the brain edema after intracranial hemorrhage (ICH) of male Sprague-Dawley rats and that the preliminary molecular mechanism may be related to the decrease of the expression levels of proinflammatory cytokines including IL-1β and TNF-α." (PMID 36545238, 2022).
lactic acidosis (5 papers, 2013 to 2025). Metabolic acidosis characterized by the accumulation of lactate in the body. "Lactic acidosis, induced by the addition of 25 mm lactic acid, also induced the release of 20-kDa IL-1β." (PMID 24022484, 2013). "M1 microglia produce pro-inflammatory cytokines such as IL-1β, TNF-α, and IL-6, which trigger the inflammatory response and cause damage such as mitochondrial oxidative phosphorylation, lactic acidosis, and excessive accumulation of free radicals, leading to neuronal necrosis." (PMID 40944219, 2025). "We also report that the addition of lactic acid directly to the culture induced the secretion of 20-kDa IL-1β, raising the possibility that lactic acidosis could drive IL-1-dependent inflammatory responses during disease." (PMID 24022484, 2013). "The acADSC treatment with 10 ng/mL TGFβ1 was able to stimulate IL1B and IL6 gene expression at a similar level to lactic acidosis." (PMID 36980280, 2023).
latent infection (5 papers, 2019 to 2024). "The Chlamydia is characterized by the latent infection of the body and the continuous secretion of cytokines, such as Tumor necrosis factor, interleukin (IL)-1β, and IL-6." (PMID 37660043, 2023). "This raises the question of whether IL-1β plays a critical role in the persistence of latent infection." (PMID 39766497, 2024). "EBV infection induces the elevation of IFI16 and NLRP3 inflammasomes in both primary and latent infections, confirming their activation by EBV and subsequent facilitation of IL-1β maturation." (PMID 38590522, 2024). "In normal to latent infections, we identified eight genes, of which three genes (FZD2, NDUFS8, NLRC4) were up-regulated, and another five genes (CCL4, IL1B, IL1A, TNF, AREG) were down-regulated." (PMID 31749827, 2019). "Additionally, during the latent infection phase of KSHV, the activation of inflammatory bodies and IL-1β inhibit the reactivation of KSHV from latency, favoring the incubation of KSHV." (PMID 38590522, 2024).
lumbar disc herniation (5 papers, 2014 to 2025). "Actually, IL1B polymorphisms have previously been associated with symptomatic lumbar disc herniation, and together with IL1RN polymorphism associated with low back pain in the general population." (PMID 25207923, 2014). "Our team demonstrated that PMD occurs in patients with lumbar disc herniation, which is related to the high levels of TNF-α, IL-6, and IL-1β in multifidus." (PMID 40722201, 2025). "LXA4 diminishes pain in the non-compressive lumbar disc herniation model by inhibiting production of pro-inflammatory cytokines (TNF-α, and IL-1β) and upregulating IL-10 and transforming growth factor-beta (TGF-β)." (PMID 37388729, 2023).
memory (5 papers, 2012 to 2025). The activities involved in the mental information processing system that receives (registers), modifies, stores, and retrieves informational stimuli. "IL1-B, a key cytokine released from glial cells, is critically involved in the pathogenesis of chronic pain, memory deficit, via activation of IL-1R1." (PMID 29069743, 2017). "Functional inhibition of IL-1β, both in mice pretreated with IL-1 receptor antagonist and in IL-1R−/− mice, mitigated the neuroinflammatory effects of surgery and memory dysfunction." (PMID 23029109, 2012). "Zeaxanthin and lutein prevented memory impairment more effectively than the positive-control resveratrol by suppressing acetylcholinesterase activity, lipid peroxidation, and pro-inflammatory cytokines (TNF-α, IL-1β)." (PMID 39337316, 2024).
Meniere disease (5 papers, 2019 to 2025). A disease of the inner ear (labyrinth) that is characterized by fluctuating sensorineural hearing loss; tinnitus; episodic vertigo; and aural fullness. "The main purpose of this study is to explore the relationship between inflammatory corpuscles of NLRP6 and serum levels of inflammatory cytokines IL-1β and IL-18 in patients with Meniere’s disease (MD) to provide a new index basis for clinical diagnosis of MD." (PMID 40837366, 2025). "Clinical and demographic variables assessed in patients with Meniere Disease with high levels of IL-1β (MDH), Meniere Disease with low levels of IL-1β (MDL), and Vestibular Migraine (VM)." (PMID 31214186, 2019).
meningioma (5 papers, 2018 to 2025). A generally slow growing tumor attached to the dura mater. "Those most investigated with respect to seizures and meningioma include IL‐1ra, IL‐1β, IL‐6, IL‐10, IFN‐γ, and TNF‐α." (PMID 40729436, 2025). "Differences in the expression of genes relating to innate immunity (such as NLRP3, IL-18 and IL-1B) between meningioma and VS were identified, with VS having a more immune-rich, inflammatory profile than meningioma overall." (PMID 41437121, 2025). "Numerous studies have shown that interleukin-1 beta (IL-1b), a pro-inflammatory cytokine in chronic inflammation has a higher level in several tumor site, including meningioma, which plays a critical role in tumor growth, metastasis, and angiogenesis." (PMID 31653130, 2019). "Other cytokines expressed in meningioma such as IL‐1β, IL‐1α, and TNF‐α have not had corresponding receptors detected yet." (PMID 40729436, 2025). "Increased level of IL-1β may subsequently trigger NF2 inactivation followed by low merlin's activity, which results in acceleration in cell growth and the development of meningioma." (PMID 30687635, 2018).
metastatic cancer (5 papers, 2013 to 2025). A carcinoma which has spread from the original site of growth to another anatomic site. "Individually, inflammatory cytokines such as OSM, IL-6, and IL-1β have been shown to promote effects associated with metastatic cancer." (PMID 31007849, 2019). "We have also shown that brain-metastatic cancer cells secrete excessive amounts of IL-1β and activate astrocytes which in turn promote Notch signalling in CSCs." (PMID 23495140, 2013). "Additionally, a combination of therapies that target both upstream activators (e.g., IL-1β, ROS) and downstream NET formation mediators could enhance therapeutic outcomes, particularly in complex conditions such as autoimmune vasculitis or metastatic cancer." (PMID 41303697, 2025). "Unlike the SW 1990 metastatic cancer cell line, in Panc 10.05, induction with LPS and ATP individually or together (L, A, and LA groups) resulted in a similar increase in the production of IL-1β." (PMID 38018872, 2023).
metastatic prostate carcinoma (5 papers, 2013 to 2025). A carcinoma that arises from the prostate gland and has spread to other anatomic sites. "Previous ex vivo and in vivo studies also have shown that lipid chaperone fatty acid-binding protein 4 and interleukin 1 beta expression in metastatic prostate carcinoma cells are markedly induced by the exposure to bone marrow adipocytes in a functional crosstalk." (PMID 35498437, 2022). "Together, our data provide evidence for functional relationship between bone marrow adiposity and metastatic prostate cancers and unravel the FABP4/IL-1β axis as a potential therapeutic target for this presently incurable disease." (PMID 24240026, 2013).